CCL2 (C-C motif chemokine ligand 2)
Diseases named in the same sentence as CCL2 in open-access papers (continued):
Sharing a sentence is not in itself a finding about the gene and the disease.
COVID-19 (continued). "MMP-7, TGF-β, CCL2, CCL-3, CXCL-10, G-CSF, IFN gamma, IL-10, IL-2, IL-4, IL-6, IL-7, TNF-α, IL-6, and IGF-1 were studied for their correlation with mortality in all 40 COVID-19 patients." (PMID 36286038, 2022). "Analysis of cytokine and chemokine expression levels revealed higher IL-1β, IL-6, TNF, and CCL2, CCL3, CCL4, and CCL7 in severe COVID-19 BALF compared to moderate disease." (PMID 35401519, 2022). "Remarkably, severe influenza and COVID-19 also converge in elevated levels of chemotactic (CXCL8, CCL2, CCL3, and CXCL10) and activating molecules (G-CSF) acting on monocytes and neutrophils." (PMID 35674675, 2022). "According to a recent meta-analysis, chemokines (CCL2, CXCL10 and CCL11) were shown to be higher in severe COVID-19 patients than in moderate cases." (PMID 35958594, 2022). "A positive correlation was found between COVID-19 BAL fluid levels of IL-15 and CXCL10 or CCL2, cytokines/chemokines involved in monocyte, lymphocyte, and NK cell functions." (PMID 34793331, 2022). "We performed quantitative real-time PCR (qRT-PCR) for representative COVID-19 related host inflammatory cytokine genes and found that a cytokine panel (including IL-6, IL-1β, TNF-α, CCL2, and CXCL9) was induced by SARS-CoV-2 infection." (PMID 34979342, 2022). "Survival analyses revealed a significant correlation between high expression of C1R, CCL2, and TNFRSF1A in the coronavirus disease-COVID-19 pathway and the poor survival in GBM patients." (PMID 35726234, 2022). "TNF-, IL-2, IL-6, IL1B, IL7, IL10, IFN-, GCSF, CXCL10, CCL2, ferritin, D-dimer, fibrinogen, leukocytosis, and C-reactive protein (CRP) levels are significantly higher in critically ill COVID-19 patients." (PMID 35645351, 2022). "The high expression levels of C1R, CCL2, and TNFRSF1A in coronavirus disease-COVID-19 pathway were significantly related to the low survival in GBM patients." (PMID 35726234, 2022). "Lower levels of miR-374a were also detected in COVID-19 patients with respect to healthy controls, while its target, CCL2, is involved in acute respiratory distress syndrome (ARDS) and cytokine storms in COVID-19 patients." (PMID 35207576, 2022). "In the moderate COVID-19 group, NEAT1 was negatively correlated with oxygen but positively with age, TUG1 expression, CCL2, TNF-α, and IL-6 expression." (PMID 35982898, 2022). "Increased expression of inflammatory SASP factors such as IL6, MCP1, and CCL2 are known to mediate excessive inflammatory response and cytokine storm of severe COVID-19 patients." (PMID 36400883, 2022). "In the severe COVID-19 group, we observed that NEAT1 expression was negatively correlated with TLC and positively correlated with TUG1 and CCL2 expressions." (PMID 35982898, 2022). "The serum cytokine profile detected in COVID-19 severe cases includes increased production of IL-2, IL-7, granulocyte–macrophage colony-stimulating factor (GM-CSF), TNF-alpha, CXCL10, MCP1/CCL2, and MIP1-alpha." (PMID 36248831, 2022). "Severe COVID-19 manifested as ARDS with elevated pro-inflammatory cytokines, involving TNF-α, IL-6, IL1B, and CCL2." (PMID 35227280, 2022). "In post-COVID-19 patients, some plasma cytokines (i.e. TNF-α, IL-18, CXCL8, CXCL10, CCL2, CCL3, and CCL4) remained higher than in HCs, but levels were much lower as compared to hospitalised patients." (PMID 36275702, 2022). "COVID-19 patients have high levels of pro-inflammatory cytokines and chemokines such as IL-1β, IL-2, IL-6, IL-7, IL-10, IFN-γ, TNF-α, G-CSF, CCL2, and CXCL10." (PMID 35782361, 2022). "In fatal COVID-19 cases, the chemokines CXCL8, CCL2, and CCL3were significantly elevated, but they were increased similarly in mild and severe cases during the early stages of infection and remained at steady levels afterwards in the mild cases." (PMID 36016187, 2022).
COVID-19 (continued). "Results of a cohort study showed that diminution of some bacterial species in patients with COVID-19 was connected to increase in the level of IL-10, TNF-α, CXCL10, and CCL2 and immunological responses." (PMID 35342407, 2022). "While responses were not different between bamlanivimab- treated individuals and those who received placebo, CCL2, CCL19, CCL20, CXCL8 and CXCL10 were upregulated in samples from the nasopharyngeal cavity and the circulating blood of patients with COVID-19." (PMID 35303909, 2022). "The concentrations of granulocyte colony-stimulating factor (G-CSF), IL-2, IL-7, IL-10, TNF, and the chemokines, CCL2, CCL3, and CXCL10 were extremely high in the plasma of patients with severe COVID-19." (PMID 36294868, 2022). "The disease is also associated with the elevated blood levels of other chemokines such as CCL2/MCP-1, CCL3/MIP-1α, CCL4/MIP-1β, CXCL9/MIG, CXCL10/IP-10 and CX3CL1/Fractalkine, which shows that CXCL1 is only one of many COVID-19 factors." (PMID 36613652, 2022). "We observed increased levels of chemokines MCP-1 (CCL2), IP-10 (CXCL10), MIP1β (CCL4) and IL-8 (CXCL8) in COVID-19 patients." (PMID 35529862, 2022). "Accordingly, higher levels of the chemokines CXCL8 (46.9 pg/ml [0.72 to 100.34] vs 15.3 pg/ml [0 to 39.8], p = 0.018) and CCL2 (590.4 pg/ml [33.8 to 1,116.8] vs 105.6 pg/ml [3.23 to 588.5]) were detected in MIS-C than in COVID-19 (p = 0.0086)." (PMID 33841438, 2021). "A previous study that examined circulating cytokine levels from people with severe COVID-19 showed a decrease in IFN-γ and increased IL-6, CXCL8, IL-1β, and CCL2, as compared to healthy controls." (PMID 34108966, 2021). "In the subsequent hyper-inflammatory phase, severe COVID-19 cases dramatically increase the levels of IL-2, IL-6, IL-7, IL-10, IP-10, CCL2 (also known as monocyte chemoattractant protein-1/MCP1), TNF-α, macrophage inflammatory protein-1α (MIP1α), and G-CSF." (PMID 34946266, 2021). "Although the profile of inflammatory markers is highly variable between patients, a general phenotype of severe COVID-19 is characterized by elevated IL-6, IL-8, IL-10, TNF-alpha, CCL2, CCL3, and CXCL8." (PMID 34830356, 2021). "We demonstrated that the CXCL10+ CCL2+ macrophages are transcriptionally similar to human blood-derived macrophages stimulated by IFN-γ and TNF-α and were expanded in severe COVID-19 lungs and inflamed RA, CD, and UC tissues." (PMID 33879239, 2021). "In our study, many of these cytokines and chemokines, especially CCL2, CXCL10, and IL6, were found to be significantly overexpressed in COVID-19 patients." (PMID 35145507, 2021). "We also observed the upregulation of IFN-γ, CCL2, IL-8, IL-12p70, IL-17a and TNF-α in COVID-19 patients compared to healthy controls." (PMID 34386007, 2021). "This process is modulated by proinflammatory mediators, such as TNFα, CCL3, and CCL2 (MCP-1), leading to hypoxia, ARDS, and possibly death for COVID-19 patients." (PMID 34616396, 2021). "Cytokines such as TNF- α, CCL2, CXCL8, and IL6, which show high levels in COVID-19 patients requiring ICU admission, can predictably be inhibited by the bioactive components." (PMID 34513735, 2021). "The results showed that in the lung tissues of patients with COVID-19, CyPA had strong positive correlations with CD68, CCL2, and IL-6." (PMID 34564690, 2021). "In consistence with previous observations, IL-6, CCL2, CXCL2, CXCL10, and IL-8 were significantly elevated in COVID-19 samples." (PMID 34103487, 2021). "Another BALF analysis found increased CCL2, CCL8, CXCL2, CXCL1, IL-33, and CCL3L1 and correlated disease severity of COVID-19 with the production of a cytokine storm." (PMID 34199761, 2021). "In this study, we showed that enriched populations of Res-like Mac (HLA-DR+ITGAM−CD68low), M1 Mac (CD68+ITGAM+CCL2+), and pro-inflammatory Mac (CD68+ITGAM−CSF1R−CCL2+) in patients with severe COVID-19." (PMID 34238338, 2021).
COVID-19 (continued). "PPI network for the immunity and inflammation cytokines in COVID-19 among R. crenulata targets showed that IL-10, IL-6, IL-1B, TNF-α, CCL2 and CXCL8 were important nodes in the network." (PMID 34313585, 2021). "The latest laboratory findings from Wuhan patients also showed that mild COVID-19 patients had elevated levels of IL-1B, IFNγ, CXCL10, and CCL2, whereas in severe cases, G-CSF, CXCL10, CCL2, and CCL3 were elevated." (PMID 34441862, 2021). "This study suggests that CCL2 and CXCL10 have the potential to be used as anti-inflammatory targets for COVID-19 therapy." (PMID 35002688, 2021). "Among these, we found two inflammatory CXCL10+ CCL2+ and FCN1+ macrophage states that are shared between COVID-19 and several of the inflammatory diseases we analyzed." (PMID 33879239, 2021). "In patients who ultimately died of COVID-19, many chemokines responsible for monocyte and T cell recruitment and survival such as CCL1, CCL2, M-CSF, IL-2, Il-16, and CCL21 were elevated, suggesting pathological roles associated with host defense factors." (PMID 34198973, 2021). "Similar to NF-κB TFs, AP-1 TFs (FOS and JUN) are critical regulators of inflammatory cytokine genes such as CCL2 and IL6, which are expressed at high levels in COVID-19 patients." (PMID 34163359, 2021). "In contrary, some important cytokines in COVID-19 cytokine storm such as CXCL10, IL-6, CCL2, CCL20, IL-8 and S100A9 showed a trend of slightly lower levels in patients with asthma in all three COVID-19 severity groups." (PMID 34238349, 2021). "In fact, patients with COVID-19 display a pro-inflammatory (IL-1β, IL-6, IL-7, IL-8, IL-9, FGF, G-CSF, GM-CSF, IFN-ɣ, CXCL10, CCL2, CCL3, CCL4, PDGF, TNFα, and VEGF) and regulatory cytokine profile (IL-10 and TGFβ; cytokine storm)." (PMID 33995342, 2021). "IL-2 was lower in COVID-19 patients than in healthy individuals, while IL-4, IL-6, CCL2, IFN-γ, and TNF-α were higher in COVID-19 patients than in healthy individuals." (PMID 34489974, 2021). "In severe COVID-19, we observed a shift in cell frequency between the FCN1+ and CXCL10+ CCL2+ macrophages (Wilcoxon rank-sum test P = 1.4e−07)." (PMID 33879239, 2021). "In severe COVID-19 lung macrophages displayed high expression of IL-1β, IL-6, TNF-α and various chemokines (CCL2, CCL3, CCL4, CCL7, CXCL9, CXCL10 and CXCL11)." (PMID 34054832, 2021). "We observed the CXCL10+ CCL2+ and FCN1+ states are abundant in severe COVID-19 compared to healthy BALF." (PMID 33879239, 2021). "The CXCL10+ CCL2+ inflammatory macrophages displayed significantly higher expression of CXCL10, CXCL11, CCL2, CCL3, GBP1, and IDO1 in severe COVID-19, inflamed RA, and CD compared to the FCN1+ macrophages." (PMID 33879239, 2021). "The analysis of its function shows that the signal receptor binding function mediated by CCL2 and MMP9 is the potential mechanism of the host factor interaction network between COVID-19 and COPD." (PMID 35002688, 2021). "IL-33, MCP-1/CCL2, and MIP-1α/CCL3 were also elevated in ICU status COVID-19 subjects over controls, consistent with other reports." (PMID 34960684, 2021). "The presence of CCL2 and CCL7 (potent chemokines for the recruitment of monocytes) were noticed to be enriched in bronchoalveolar fluid (BALF) from severe COVID-19 patients." (PMID 33981235, 2021). "The limited data suggests that COVID-19 pregnancies have similar elevations of cytokines (IL-6, TNFα) and chemokines (CCL2, CXCL10) as other COVID-19 patients." (PMID 33168125, 2021). "Levels of IL-6, IL-10, IL-15, IFN-γ, TNF-α, CCL2, CCL3, CCL4, CCL26, CXCL9 and CXCL10 were significantly elevated both in COVID-19 critical clinical condition and in MAS patients as compared to healthy controls." (PMID 34226537, 2021). "SARS-CoV-2-infected cells treated with famotidine demonstrate reduced expression levels of the inflammatory mediators CCL-2 and IL6, drivers of the cytokine release syndrome that precipitates poor outcome for patients with COVID-19." (PMID 34214498, 2021).
COVID-19 (continued). "Cytokine profiling of critical COVID-19 patients reflects MAS with high levels of pro-inflammatory cytokines and chemokines such as IL-6, IL-7, Tumour Necrosis Factor (TNF-α), CCL2, CCL3, CXCL10, and IL-2 receptor." (PMID 33178021, 2020). "Consistent with this notion, plasma levels of CCL-2 and IP-10 were elevated earlier than IL-6 in intensive care unit (ICU) COVID-19 patients." (PMID 32766256, 2020). "It was first reported that several pro-inflammatory cytokines and chemokines, including IL-2, IL-7, IL-10, CXCL10 (IP-10), CXCL8, CCL2 (MCP1), TNFα, and IFNγ were higher in the plasma of COVID-19 patients as compared to healthy controls." (PMID 33363221, 2020). "Among 41 hospitalized COVID-19 patients in Wuhan, China, all had elevated IL-1B, IP10/CXCL10, and MCP1/CCL2." (PMID 32545518, 2020). "The current data suggest that chemokines such as CCL2, CCL3, CCL5, and IP10 are the initiators of the deadly COVID-19 immunopathological pathway." (PMID 32766256, 2020). "The expression of several cytokines identified in the current study (i.e., IL1B, IL-6, TNF, CCL2, CXCL9, and CXCL10) were also seen in bronchoalveolar lavage (BAL) cells from COVID-19 patients, providing further support to our observation." (PMID 32882823, 2020). "CCL2 and CCL7, as two potent chemokines for recruiting CC- chemokine receptor 2-positive (CCR2+) monocytes, were found in the BALF of severely infected COVID-19 patients." (PMID 33584679, 2020). "The macrophage cluster-1-derived signature (CCL8, CCL3, CCL2, KLF6, and SPP1) was confirmed to be significantly higher in severe cases of COVID-19 compared to control and mild cases." (PMID 33138195, 2020). "This decline in CCL2 and CCL3 might revert T cell exclusion and the cytokine storm thereby affecting COVID-19 severity." (PMID 40055791, 2025). "Moreover, increased fold changes of CCL2, CCL3, IL-1Ra, and VEGF were commonly observed only in convalescent COVID-19 (Early, Intermediate, and Late subgroups) (# below bar charts)." (PMID 40821818, 2025). "Moreover, the roles of CCL2 and CXCL10 extend beyond simple chemotaxis; they are intricately involved in the pathophysiological mechanisms that drive the progression of COVID-19 to its more severe forms." (PMID 39203987, 2024). "As expected, performing TPE decreased the amount of anti-type I IFN auto-antibodies and improved the elimination or limited the production of certain inflammatory mediators (IL-18, IL-7, CCL2, CCL3, etc.)circulating in the blood of COVID-19 patients, compared to ST controls." (PMID 39896810, 2024). "Levels of CCL2 and CCL8 in BAL fluid as well as CXCL10 in plasma samples collected during the first 48 hours of intubation were higher in patients with COVID-19 relative to all other groups, with the exception of patients with other viral pneumonias (q < 0.05, Mann-Whitney)." (PMID 38502186, 2024). "This may explain the increase in ITAC (CXCL11), MCP1 (CCL2) and MIP3b (CCL19) in individuals with long COVID-19 in our study, as these SIM are mainly expressed by monocytes, macrophages or dendritic cells." (PMID 39578604, 2024). "COVID-19 can induce cytokine storms, such as IL6, IL32, CD83, CCL2, CXCL11, the TNF family (TNFSF9 and the receptor TNFRSF9), and integrin-related genes, which exacerbates COVID-19 related myocarditis and decreases the prognosis of patients requiring ECMO treatment." (PMID 39026189, 2024). "Additionally, studies have demonstrated that in COVID-19 patients, the increase in viral load corresponds to the upregulation of critical chemokines, including CCL7, CCL2, CXCL8, and others." (PMID 38812521, 2024). "Moreover, in COVID-19 patients, increased mRNA expression levels of CXCL10, CCL2, and TNF were correlated with an increased number of MKs27,28." (PMID 38519457, 2024).
COVID-19 (continued). "Finally, qRT-PCR analyses revealed that the pro-inflammatory cytokines CCL2 and CXCL10 whose expression is correlated with severe COVID-19 (reviewed in52) were significantly reduced in KYA1797K and E7449-treated animals." (PMID 40295745, 2024). "Indeed, we and others previously found that COVID-19 patients with neurological complications had elevated serum immune mediators and cytokines (IL-6, IL-12p40, IL1-RA, M-CSF, CCL2, and HGF) which correlated with serum brain injury markers." (PMID 39474424, 2024). "According to the literature, higher levels of CCL2 and CCL3 also play a role in COVID-19 severity." (PMID 37908356, 2023). "The Cox regression analyses suggested that 9 prognostic genes (ANPEP, OAS1, SCGB1A1, HLA‐A, NPPB, FGB, CCL2, TLR4, and SERPINE1) might act critical roles in the treatment of UCEC/COVID-19." (PMID 36969077, 2023). "The downregulation of the NF-κB/MAPK signaling pathway was postulated to decrease pro-inflammatory cytokines such as IL-6, TNF-α, IL-1β, CXCL10/IP-10, CCL2/MCP-1, and IL-8, suggesting that it may prevent cytokine storm in COVID-19." (PMID 37298539, 2023). "Then, regression analyses indicated that 9 prognostic genes (including ANPEP, OAS1, SCGB1A1, HLA‐A, NPPB, FGB, CCL2, TLR4, and SERPINE1) might play important roles in quercetin for treating UCEC/COVID-19." (PMID 36969077, 2023). "We believe that the C1R, CCL2, and TNFRSF1A genes in the coronavirus-COVID-19 pathway may be activated in GBM patients, making GBM patients more susceptible to novel coronavirus infection." (PMID 35726234, 2022). "SARS-CoV-2 infection induced CCL2, CCL5 and IL-6 release from placental cells, which might promote the cytokine storm in pregnant women with COVID-19." (PMID 36414950, 2022). "Controversially, another study indicated that in severe COVID-19 cases, peripheral blood monocytes significantly increased expression of IL-6, TNF, IL-1β, and their receptors, as well as pro-inflammatory chemokines including CCL2, CCL3, and CCL4." (PMID 35632823, 2022). "Finally, COVID-19 worsening during hospitalization is also positively correlated with admission plasma levels of IL-8/CXCL8, MCP-1/CCL2, IL-10, and C-reactive protein." (PMID 36035415, 2022). "Subsequently, Paxlovid was analyzed against the core targets of LUAD/COVID-19 (CXCL2, CCL2, IL12B, CSF3, LBP, IL6, CXCL10) and Paxlovid, and the results showed that IL-6, IL12B, LBP and Paxlovid could be combined." (PMID 36157452, 2022). "Furthermore, CCL2, IL-6, and TNF-α expressions were higher in COVID-19 patients compared to controls (P<0.001)." (PMID 35982898, 2022). "Therefore, more research on the antagonism of CXCL8, CCL2, CCL3, and CXCL10 in influenza and COVID-19 is required." (PMID 35674675, 2022). "Therefore, CXCL8, CCL2, and CMV seropositivity should be considered as new prognostic factors for severe COVID-19 courses." (PMID 36232655, 2022). "Furthermore, several innate cytokines, such as IP-10, MCP-1, CCL2, TNF-α, and MIP-1A, were elevated in COVID-19 patients, who required ICU care." (PMID 35715852, 2022). "Targeting airway-derived cytokines, such as CCL2, via a CCR2 antagonist may be effective in reducing lung damage and preventing further respiratory sequelae in severe COVID-19." (PMID 35749425, 2022). "Findings from mouse models, cellular systems, and samples from patients with SARS-CoV-2-induced COVID-19 have shown massive generation of C5a, CCL chemokines (e.g., CCL2, CCL3, and CCL5), CXCL chemokines (e.g., CXCL9 and CXCL10), and growth factors, i.e., TGFβ, GCSF, GMCSF, VEGF, FGF, and PDGF." (PMID 36430817, 2022). "Additionally, the level of multiple chemokines (IL-12p40, CCL2, CCL7, CXCL10, and M-CSF) was significantly increased in fatal COVID-19 cases." (PMID 35386707, 2022).